CLDN8 (claudin 8)
Description:
Can associate with other claudins to regulate tight junction structural and functional strand dynamics (By similarity). May coassemble with CLDN4 into tight junction strands containing anion-selective channels that convey paracellular chloride permeability in renal collecting ducts (By similarity). Cannot form tight junction strands on its own.
Synonyms: HEL-S-79
Tractability: Antibody: UniProt places it where antibodies can reach, with medium confidence; UniProt predicts a signal peptide or a membrane-spanning region; its Gene Ontology location is reachable by antibodies, with medium confidence. PROTAC: UniProt records ubiquitination sites on it.
Gene: Protein-coding gene on chromosome 21 (30,214,006 to 30,216,097, reverse strand). Ensembl gene ENSG00000156284.
Subcellular location: Cell junction, tight junction; Cell membrane
Pathways (Reactome):
Cell-Cell communication: Tight junction interactions
Gene Ontology:
Molecular function: protein binding; identical protein binding; paracellular tight junction channel activity; structural molecule activity
Biological process: calcium-independent cell-cell adhesion; paracellular transport
Cellular component: endoplasmic reticulum; plasma membrane; bicellular tight junction; apicolateral plasma membrane; basolateral plasma membrane; membrane
Genetic constraint (gnomAD): Loss-of-function variants: 3 observed, 2.92 expected, observed/expected ratio (o/e) 1.03, 90% interval 0.44 to 1.87. That is too few expected variants to judge how well the gene tolerates losing a copy. Missense variants: 314 observed, 293.66 expected, observed/expected ratio (o/e) 1.07, 90% interval 0.97 to 1.17. Synonymous variants: 107 observed, 111.6 expected, observed/expected ratio (o/e) 0.96, 90% interval 0.82 to 1.13.
Homologues: Orthologues: chimpanzee CLDN8 (99% identical), macaque CLDN8 (97% identical), dog CLDN8 (84% identical), pig CLDN8 (84% identical), rabbit CLDN8 (83% identical), mouse Cldn8 (83% identical), rat Cldn8 (81% identical), guinea pig CLDN8 (80% identical), zebrafish cldn8.3 (42% identical), tropical clawed frog cldn17 (38% identical), tropical clawed frog cldn17.3 (34% identical). Paralogues in human: CLDN17 (56% identical), CLDN9 (46% identical), CLDN3 (46% identical), CLDN6 (44% identical), CLDN4 (41% identical), CLDN5 (40% identical), CLDN7 (40% identical), CLDN14 (35% identical), CLDN1 (34% identical), CLDN19 (34% identical), CLDN2 (32% identical), CLDN10 (31% identical), and 10 more.
Diseases named in the same sentence as CLDN8 in open-access papers:
CLDN8 is named in the same sentence as 50 diseases in open-access papers, as found by Europe PMC text mining. Sharing a sentence is not in itself a finding about the gene and the disease. The quoted sentences say what the papers report.
colitis (13 papers, 2011 to 2024). Inflammation of the colon. "We found that DSS-induced colitis was associated with decreased expression of colonic claudin-1, claudin-3, claudon-5, claudin-7 and claudin-8, and also increased expression of colonic claudin-2." (PMID 22073304, 2011). "A significant increase in mRNA expression for ZO-1 and Cldn8 and significant decrease in the expression of Cldn4 and Muc2 mRNAs were observed in the group of obese animals with colitis forced to participate in treadmill exercise (p < 0.05)." (PMID 38255781, 2024). "Further in vivo study found that miR-223 is a key mediator in the communication between the IL-23 pathway through targeting claudin 8 and administration of its antagomir to restore claudin 8 level, improve intestinal barrier, and ameliorate DD-induced colitis." (PMID 39259390, 2024). "The mRNA expression of ZO-1, Cldn4 and Cldn8 was significantly increased while the Muc2 mRNA expression was significantly decreased in the IAP-treated forced-exercise TNBS colitis rats fed an SD (p < 0.05)." (PMID 38255781, 2024). "Claudin 8 and claudin 12 had decreased expression in colitis, consistent with the literature, and TGS 121 treatment had no influence." (PMID 33803793, 2021). "Antagomir inhibition of miR-223 reactivated CLDN8 and improved a number of signs associated with TNBS-induced colitis in mice." (PMID 27029486, 2016). "Upregulation of CLDN8 by anti-IL23P19 was also confirmed in mice with colitis as compared with the isotype controls using IHC staining." (PMID 27029486, 2016). "Therapeutic treatment of colitis in mice using an IL23 antibody restored CLDN8 abundance, in parallel with recovery from colitis." (PMID 27029486, 2016). "By reducing miR-223 with the antagomir, we observed a parallel increase of CLDN8 in the colitis model." (PMID 27029486, 2016). "Intensity of claudin-7 and claudin-8 immunostaining was markedly decreased in colitis group, and moderately elevated after treatment with AMD3100." (PMID 22073304, 2011). "The expressions of colonic claudin-1, claudin-3, claudin-5, claudin-7 and claudin-8 in colitis mice were markedly decreased as compared with control mice." (PMID 22073304, 2011). "Treated with CXCR4 antagonist AMD3100 significantly promoted colonic claudin-1, claudin-3, claudin-5, claudin-7 and claudin-8 expressions, and also decreased colonic claudin-2 in colitis mice." (PMID 22073304, 2011). "Our study revealed that, in IAP-treated mice with colitis, both Cldn4 and Cldn8 were upregulated." (PMID 38255781, 2024). "Importantly, we demonstrate that knockdown of miR-223 restores CLDN8 levels in mice with colitis and that it mitigates progression of colitis." (PMID 27029486, 2016). "Similarly, in the colitis animal model we observed the downregulation of CLDN8 in TNBS-induced colitis tissues." (PMID 27029486, 2016). "Moreover, in the present study, we found that treated with CXCR4 antagonist AMD3100 significantly promoted colonic claudin-1, claudin-3, claudin-5, claudin-7 and claudin-8 expressions, and also decreased colonic claudin-2 in colitis mice." (PMID 22073304, 2011). "Therefore, some of the beneficial effects of P100K milk EVs on colitis might come from the reduction of the IL-9/miR-21/CLDN8 pathway, which would impact RhoB, reduce gut permeability and modulate the microbiota." (PMID 31601878, 2019). "CLDN8 was reported to be significantly downregulated in the biological colon of IBD patients, and similar results were observed in colitis mice." (PMID 36388363, 2022). "It is reported that IL-23 downregulates CLDN8 in both IBD patients and mice with colitis by upregulating miR223." (PMID 34680308, 2021). "The authors observed that the inhibition of miR-223 restored CLDN8 expression, restored barrier function, and alleviated inflammation, resulting from TNBS-induced colitis." (PMID 34571853, 2021). "Our data thus identify CLDN8 as a novel gene target both in IBD patients and in the anti-IL23P19-treated colitis animal model." (PMID 27029486, 2016).
colitis (continued). "In this study, we show that CLDN8 was downregulated in both IBD patients and in mice with TNBS-induced colitis under the control of miR-223." (PMID 27029486, 2016). "CLDN8 was significantly downregulated in IBD patients with inflamed colonic mucosa, and in trinitrobenzene sulphonic acid (TNBS) induced colitis in mice." (PMID 27029486, 2016). "Our present study also demonstrated that AMD3100 increased the expression of colonic claudin-1, claudin-3, claudon-5, claudin-7 and claudin-8, decreased of colonic claudin-2 expression in DSS-induced colitis." (PMID 22073304, 2011). "In rats with TNBS-induced colitis, diet supplementation with grape peel powder rich in polyphenols and fiber or with fish oil rich in ω-3 PUFAs strongly upregulated the ZO-1, CLDN1, CLDN5 and CLDN8 protein expressions in colon." (PMID 33806347, 2021).
Crohn disease (9 papers, 2015 to 2025). A gastrointestinal disorder characterized by chronic inflammation involving all layers of the intestinal wall, noncaseating granulomas affecting the intestinal wall and regional lymph nodes, and transmural fibrosis. "Of note, genes implicated in Crohn’s disease such as Cldn8 (encodes tight junction protein claudin 8) and Tnfsf15 were also downregulated in SERT KO mice." (PMID 29666456, 2018). "Downregulation and redistribution of claudin-8 along with claudin-5 lead to alterations in tight junction’s structure and pronounced barrier dysfunction both in mild and moderately active Crohn’s disease." (PMID 33364202, 2020). "Reduced claudin 8 expression has been observed in diseases of intestinal barrier dysfunction such as Crohn’s disease and in autism models where dysbiosis is also evident." (PMID 26154283, 2015). "Furthermore, it has been shown that CLDN8 expression was downregulated and redistributed off the tight junction in patients with active Crohn’s disease that is typified by impaired intestinal barrier function." (PMID 41321497, 2025). "Moreover, both occludin and claudin-8 were shown to be downregulated and redistributed from the cellular junctions in patients with active Crohn’s disease." (PMID 38334616, 2024). "Claudin-8 is a tight junction protein that decreases paracellular permeability, and lack of claudin-8 expression has been previously associated with Crohn’s disease and gut barrier dysfunction." (PMID 34296202, 2021). "In patients with Crohn’s disease, the expression of CLDN2 is dramatically up-regulated, especially in patients with low expression of the sealing tight junction protein CLDN8 (claudin 8)." (PMID 26589571, 2015).
colon cancer (7 papers, 2017 to 2023). "Its overexpression promoted the occurrence and development of colon cancer by competitively binding with miR-340-5p to regulate CLDN8/IL22 co-expression and activating ERK signaling pathway." (PMID 34659345, 2021). "Another study suggested that LINC00662 competitively binds to miR-340-5p to modulate the expression of CLDN8/IL22 in colon cancer." (PMID 34048366, 2021). "Combined with the previous results, the effects of LINC00662 overexpression and CLDN8 overexpression on the biological function of colon cancer cells were consistent." (PMID 31900207, 2020). "LINC00662 overexpression promoted the occurrence and development of colon cancer by competitively binding with miR-340-5p to regulate CLDN8/IL22 co-expression and activating ERK signaling pathway." (PMID 31900207, 2020). "Our previous studies have shown that CLDN8 promotes the proliferation and metastasis of colon cancer cells by activating MAPK/ERK signaling pathway." (PMID 31900207, 2020). "Our previous study found that CLDN8 was overtly up-regulation in colon cancer tissues and cell lines, promoting cell proliferation, migration and invasion by activating MAPK/ERK signaling pathway." (PMID 31900207, 2020). "Both IL22 and CLDN8 are target genes of miR-340-5p and are co-expressed in colon cancer cells." (PMID 31900207, 2020). "Previous research showed that lncRNA LINC00662 overexpression targeting miR-340-5p/CLDN8/IL22 axis promoted proliferation, migration, and invasion and suppressed apoptosis of colon cancer cells via activating the ERK signaling pathway in vitro and in vivo." (PMID 35571488, 2022). "Through western blot assay, we found that the high expression of LINC00662 significantly increased the expression of CLDN8 and IL22 in protein level and activated the ERK signaling pathway in colon cancer cells." (PMID 31900207, 2020). "INC00662 may be a potential proto-oncogene by regulating the co-expression of CLDN8/IL22 through competitively binding to miR-340-5p to affect the occurrence and development of colon cancer." (PMID 31900207, 2020). "However, the high expression of LINC00662 up-regulated the protein levels of CLDN8 and IL22 in colon cancer cells and activated ERK signaling pathway were markedly reversed by miR-340-5p overexpression." (PMID 31900207, 2020).
colorectal cancer (7 papers, 2019 to 2024). A primary or metastatic malignant neoplasm that affects the colon or rectum. "Similarly, CLDN8 was also associated with colorectal cancer prognosis." (PMID 38532103, 2024). "On the other hand, as CLDN8 is correlated with cancer progression via Akt and MAPK signaling in prostate cancer, the significance of downregulated claudin-8 in colorectal cancer awaits further analysis." (PMID 31316506, 2019). "The MAPK/ERK signaling pathway is activated in colorectal cancers when CLDN8 is overexpressed." (PMID 35281827, 2022). "In contrast, Claudin-8 was highly expressed in desmoplastic colorectal cancer liver metastases." (PMID 34079064, 2021). "Here, using real gene expression data, we applied CSER to construct a colorectal cancer GRN and successfully identified several key regulatory genes closely related to colorectal cancer (CRC), including ADAMDEC1, CLDN8, and GNA11." (PMID 39371416, 2024). "In contrast to our observation, CLDN8 was previously reported to be overexpressed in CRC patients and promoted cell proliferation, migration, and invasion of colorectal cancer cells." (PMID 36293321, 2022). "The signaling connection between MAPK and claudin-8 was shown in Yersinia enterocolitica infection and JNK and colorectal cancer and ERK." (PMID 31936044, 2020). "Our findings revealed that the mRNA expression levels of CLDN1, CLDN2, CLDN12, and CLDN14 were upregulated in colorectal cancer tissues relative to normal tissues in the Oncomine database, whereas CLDN3, CLDN5, CLDN7, CLDN8, CLDN11, CLDN15, and CLDN23 were downregulated, as previously reported." (PMID 35281827, 2022).
psoriasis (4 papers, 2012 to 2025). An autoimmune condition characterized by red, well-delineated plaques with silvery scales that are usually on the extensor surfaces and scalp. "•Study reveals new psoriasis mechanism: hsa-miR-31-3p/CLDN8 axis linked to skin barrier dysfunction." (PMID 40160514, 2025). "•Psoriasis lesions show high hsa-miR-31-3p, causing CLDN8 downregulation, a key tight junction protein." (PMID 40160514, 2025). "A recent study has shown that miR-31-3p also regulates the barrier function by interacting with CLDN8 (Claudin-8) in psoriasis." (PMID 41296428, 2025). "This study investigates the role of hsa-miR-31-3p in regulating skin barrier function through its interaction with claudin-8 (CLDN8) in psoriasis." (PMID 40160514, 2025). "Analysis of psoriasis transcriptome sequencing datasets revealed a marked decrease in CLDN8 expression coupled with a substantial increase in hsa-miR-31-3p levels within psoriatic lesions." (PMID 40160514, 2025). "This study investigates the potential mechanism by which hsa-miR-31-3p may impair skin barrier function in psoriasis through its interaction with CLDN8." (PMID 40160514, 2025). "By targeting the hsa-miR-31-3p/CLDN8 pathway, it may be possible to restore skin barrier function in psoriasis patients, potentially improving disease outcomes and quality of life." (PMID 40160514, 2025). "we hypothesized a similar mechanism in psoriasis involving CLDN8 (Ranking 17th among differentially expressed genes with low expression)." (PMID 40160514, 2025). "Based on these findings, we speculate that hsa-miR-31-3p may likely influence the skin barrier in psoriasis by regulating CLDN8." (PMID 40160514, 2025). "•CLDN8 downregulation damages skin barrier, driving psoriasis development and progression." (PMID 40160514, 2025). "Claudin 8 (Cldn8) is a known epidermal protein involved in tight junctions, and was identified by RNAseq as being relevant to the immune response in atopic dermatitis and psoriasis." (PMID 34823472, 2021). "However, how CLDN8 is regulated and its specific impact on the skin barrier in psoriasis remains unclear." (PMID 40160514, 2025). "Functional studies demonstrated that both CLDN8 knockdown and hsa-miR-31-3p overexpression compromised the permeability barrier of keratinocytes, suggesting a mechanistic link between elevated hsa-miR-31-3p levels, reduced CLDN8 expression, and skin barrier dysfunction in psoriasis." (PMID 40160514, 2025). "This suggests that CLDN8 may play an important role in skin barrier dysfunction in psoriasis." (PMID 40160514, 2025). "•Targeting hsa-miR-31-3p/CLDN8 pathway could lead to new treatments for psoriasis patients." (PMID 40160514, 2025). "Furthermore, in an imiquimod-induced psoriasis mouse model, administration of mmu-miR-31-3p antagomir effectively ameliorated skin barrier damage, reduced inflammatory manifestations, and restored CLDN8 expression." (PMID 40160514, 2025). "Our findings suggest that hsa-miR-31-3p downregulates CLDN8 expression by binding to its 3′UTR, potentially contributing to skin barrier dysfunction in psoriasis patients." (PMID 40160514, 2025). "Recent studies have reported that tight junction (CLDN8) and lipid biosynthesis and metabolism (FA2H and ALOXE3) products are significantly downregulated in both atopic dermatitis and psoriasis." (PMID 40160514, 2025). "Several genes in the psoriasis classifier, KYNU (up), MUC7 and CLDN8 (down), were part of the Etanercept “molecular scar” previously reported by our group." (PMID 22957057, 2012).